INS (insulin)
Diseases named in the same sentence as INS in open-access papers (continued):
Sharing a sentence is not in itself a finding about the gene and the disease.
diabetes (continued). "Diabetic ketoacidosis (DKA) is a severe acute metabolic complication of diabetes characterized by the excessive synthesis of ketone bodies due to insulin insufficiency, posing a life-threatening risk." (PMID 39598463, 2024). "For instance, coronary heart disease resulting from impaired insulin metabolism can lead to dyslipidaemia, a risk factor for cardiovascular complications in diabetes." (PMID 38786121, 2024). "Beyond their anti-inflammatory effects, these therapies improve insulin sensitivity and lipid metabolism, addressing critical aspects of diabetes management and reducing cardiovascular risk." (PMID 38540270, 2024). "Various parameters, including diabetes induction rates, average insulin doses, extent of weight loss, and adverse effects such as diabetic ketoacidosis (DKA), were measured." (PMID 39070316, 2024). "In this study, among participants with known diabetes, moderate weight loss had lower likelihood of insulin use." (PMID 39064637, 2024). "Diabetes mellitus (DM) is a frequent condition of the endocrine system that appears due to a deficiency of insulin secretion or the resistance of peripheral tissues to its action." (PMID 39124656, 2024). "Diabetes mellitus comprises a cluster of metabolic disorders characterized by hyperglycemia resulting from deficiencies in insulin secretion, insulin action, or both." (PMID 39298755, 2024). "Diabetes increases the risk of falls in the elderly, especially those on insulin, where the risk of falls is 94% higher than in non‐diabetic elderly." (PMID 38571669, 2024). "The loss of the first-phase insulin response to intravenous glucose is one of the earliest detectable defects of β-cell dysfunction in prediabetes and type 2 diabetes mellitus." (PMID 38791525, 2024). "Diabetes is a metabolic disease that leads to hyperglycemia caused by two main factors: defective insulin secretion and impaired insulin action or both." (PMID 39201799, 2024). "A primary focus involves the development of next-generation nanocarriers with enhanced targeting capabilities, allowing for precise delivery of insulin to specific tissues or cells associated with diabetes pathophysiology." (PMID 39065795, 2024). "If the blood glucose level is higher than normal but nothigh enough to diagnose diabetes, this condition is defined as prediabetes.Adiponectin increases fatty acid oxidation and insulin sensitivity and isclosely associated with obesity." (PMID 38655997, 2024). "These animals acquire diabetes due to genetic mutations that impact insulin production or signalling pathways." (PMID 39204115, 2024). "Longer duration of diabetes (over 10 years), insulin treatment, and complications were associated with lower QoL and physical health." (PMID 38769507, 2024). "Outcomes of interest encompass diabetes remission defined as achieving normal blood glucose levels absent any diabetes medications as well as metrics of glycemic control, insulin sensitivity, weight loss achievements, and other metabolic effects." (PMID 39735002, 2024). "A temporary rise in FFAs in pancreas causes insulin secretion, but a permanent increase leads to the dysfunction of β-cell and ultimately death of cells and induces diabetes." (PMID 39133724, 2024). "Those women who were treated with insulin during pregnancy and who subsequently developed overt diabetes showed an exacerbation of the risk estimates." (PMID 39389786, 2024). "Diabetes mellitus (DM) is a chronic metabolic disease characterized by increased blood glucose caused by insulin resistance or insufficient insulin secretion." (PMID 38515506, 2024). "Nevertheless, the authors did note a significant reduction in TNF-α and fasting plasma insulin, which have both been posited as mediators in numerous diabetes-associated complications." (PMID 38844885, 2024). "In 1971, the Diabetes Association of Sri Lanka (DASL) established a single-centre insulin bank for T1D and identified 686 patients." (PMID 39720308, 2024).
diabetes (continued). "The patient carrying such a variant presented an early onset diabetes diagnosed at 8 years old and underwent insulin treatment." (PMID 39201476, 2024). "This is contrary to the more common form of ketoacidosis seen in people with diabetes due to insulin deficiency, which is treated with the administration of parenteral insulin." (PMID 39221223, 2024). "A splice variant of MADD that skips exon 30 causes diabetes and hypopituitarism and affects insulin and luteinizing hormone production a mouse model." (PMID 38775154, 2024). "Pancreatic islet β-cells function is closely associated with diabetes, and insufficient insulin secretion caused by pancreatic β-cells failure contributes to hyperglycemia." (PMID 39415790, 2024). "Gluco/lipotoxicity associated with diabetes also induces ER stress and excess Ca2+ release into the cytosol, further impairing mitochondria and insulin secretion." (PMID 38404962, 2024). "Of note, although insulin amyloidosis is uncommon in mammals, several cases of amyloid deposits derived from insulin at injection sites have been linked to diabetes mellitus." (PMID 39858435, 2024). "β Cell–specific deletion of OGT causes diabetes in part by reduced β cell mass and insulin secretion associated with a decreased number of insulin granules and mitochondrial dysfunction." (PMID 39388284, 2024). "The pathogenesis of diabetes involves insulin deficiency (secretion and/or synthesis) and abnormal insulin response." (PMID 38890991, 2024). "Because most oral anti-hyperglycemic drugs are contraindications for patients with diabetes and HD, insulin therapy is the main treatment option for these patients, but insulin therapy is a strong risk factor for hypoglycemia and hyperglycemia crisis." (PMID 39628691, 2024). "Diabetes mellitus (DM) complications are a burden to health care systems due to the associated consequences of poor glycemic control and the side effects of insulin therapy." (PMID 38675446, 2024). "Older or frail adults with diabetes are at greater risk and more vulnerable in the context of insulin errors." (PMID 39666732, 2024). "The main concern is that AIns causes poor glycemic control and leads to increased insulin dosage in patients with diabetes due to impaired insulin absorption." (PMID 39858435, 2024). "Hyperglycemia, the hallmark of diabetes, results from a diminished ability of the body to produce or respond to insulin, making it a complex metabolic disorder." (PMID 38669398, 2024). "Based on such a concept, understanding which insulin actions are deficient and which are excessive in individuals with diabetes will lead to the optimization of treatment." (PMID 39513056, 2024). "Low carbohydrate diet as well as Mediterranean, DASH and high-fiber diets can improve insulin sensitivity and reduce blood sugar levels which reduces the risk of AFib complications in people with diabetes." (PMID 39149585, 2024). "The FTO gene’s impact varied with surgery type and duration, with some polymorphisms linked to weight loss differences, insulin levels, and diabetes risk." (PMID 39125390, 2024). "The TyG index, a measure of insulin sensitivity, has emerged as a significant risk factor for various metabolic disorders, including diabetes, pre-diabetes, obesity, CVD and renal insufficiency." (PMID 39309107, 2024). "Endocrine disorders are common in patients with diabetes, particularly characterized by a deficiency in insulin and insulin-like growth factor-1 (IGF-1), which leads to insufficient collagen synthesis and poor bone mineralization." (PMID 39194658, 2024). "In keeping with previously published results, monotherapy with metformin was associated with weight loss after diabetes diagnosis, and treatment with sulfonylureas, thiazolidinediones or insulin was associated with weight gain." (PMID 38967665, 2024).
diabetes (continued). "About 90% of diabetes cases are type 2 diabetes, which is characterized by decreased insulin levels, β-cell dysfunction, insulin resistance, and the eventual loss of β-cells." (PMID 39398666, 2024). "Insulin therapy was linked to a longer duration of diabetes, a greater HbA1c level, and an increased fasting blood glucose level." (PMID 39495998, 2024). "In the guidelines of the Canadian Diabetes Association, insulin remains the gold standard, while metformin is considered as an alternative approach only in patients with GDM." (PMID 37798604, 2024). "Since5-HT is coreleased with insulin, this behavior can therefore alsobe linked to insulin exocytosis and diabetes, making the finding valuablefor diabetes and diabetic research." (PMID 39713028, 2024). "Herein we describe a patient with diabetes caused by the heterozygous pathogenic variant R46Q in the insulin gene and the glycemic response to selected antidiabetic treatment regimens." (PMID 39027635, 2024). "Univariable logistic regression analysis indicated that diabetes, fasting glucose, fasting insulin and HOMA-IR index BMI were statistically associated with MACCEs." (PMID 39590197, 2024). "Diabetes mellitus is a chronic metabolic disorder that can cause elevated blood glucose levels due to impaired insulin secretion or resistance." (PMID 39723093, 2024). "Improvements in HOMA-IR further support the interventions’ role in enhancing insulin sensitivity, potentially reducing the risk of diabetes progression and associated complications." (PMID 39598283, 2024). "Diabetic retinopathy is one of the most common microvascular diseases in diabetes, which is essentially caused by abnormal blood glucose metabolism caused by insufficient insulin secretion or decreased activity." (PMID 38956257, 2024). "Calorie restriction extends lifespan in model organisms and reduces age-associated parameters, including fat mass, blood pressure, inflammation and insulin levels, which are risk factors for diabetes, cardiovascular disease or cancer." (PMID 39713269, 2024). "A low-GI diet improves insulin sensitivity, lowers plasma triglyceride levels, reduces the risk of diabetes and heart disease, and helps treat obesity." (PMID 38257126, 2024). "Diabetes is a chronic metabolic disorder characterized by hyperglycemia, caused by either abnormal insulin secretion or insulin resistance, and represents a significant and growing global public health concern." (PMID 39599684, 2024). "These biomarkers can provide more in-depth information about the duration of hyperglycemia, the risk of complications, and the insulin-related causes of diabetes, which are impaired insulin secretion or insulin production and insulin resistance." (PMID 39091901, 2024). "It aids in obesity and diabetes management by promoting weight loss, enhancing glucose metabolism, and improving insulin sensitivity." (PMID 38847940, 2024). "Type 2 diabetes mellitus (T2DM) is a metabolic disorder caused by a combination of defective insulin secretion by pancreatic β-cells and the inability of tissues to appropriately respond to insulin." (PMID 39795155, 2024). "For instance, there is a documented risk of insulin aggregation into cytotoxic amyloid fibrils, especially in diabetes patients." (PMID 39275349, 2024). "None of the patients with diabetes who were on oral hypoglycemics alone at baseline had admissions for a diabetes-specific reason; however, two had admissions for other causes that were complicated by hyperglycemia requiring short-term insulin use." (PMID 38392055, 2024). "Iron metabolism disorders significantly increase the risk of diabetes and its related complications by inducing oxidative stress, inflammation, insulin resistance, and disturbances in glucose and lipid metabolism." (PMID 39430450, 2024). "•mt-tRF-LeuTAA silencing leads to impaired metabolism-insulin secretion coupling, a hallmark of diabetes." (PMID 38704026, 2024).
diabetes (continued). "Diabetes mellitus is a metabolic disorder caused by an absolute or relative deficiency of insulin, which is a debilitating and costly disease with multiple serious complications." (PMID 38774757, 2024). "This double-blind, randomized, placebo-controlled, multicenter feasibility clinical trial aimed to determine the safety of oral 8 mg insulin in patients with metabolic dysfunction-associated steatohepatitis and type 2 diabetes mellitus." (PMID 39131144, 2024). "Taken together, these results indicate that insulin deficiency modulates processes in the mouse brain relevant to STZ-induced diabetes." (PMID 39139674, 2024). "Increasing physical activity (PA) levels emerges as a promising avenue toaddress AF risk factors, such as obesity, hypertension, and diabetes mellitus,through mechanisms of reduced vasoconstriction, endothelin-1 modulation, andimproved insulin sensitivity." (PMID 39139428, 2024). "In this study, we found that Tipe1 deficiency in islet β cells led to pre‐diabetes phenotype, including glucose intolerance and impaired insulin secretion under physiological conditions." (PMID 38417114, 2024). "Increased glucose exposure was associated with a higher prevalence of diabetes in acromegaly GH-Par, with a similar (considering concentration) but late (1 h) insulin peak in respect to GH-NPar." (PMID 37344722, 2024). "Diabetes Mellitus (DM) is chronic hyperglycemia characterized by a deficiency in insulin secretion, insulin activity, or both." (PMID 38187330, 2024). "General population is not taking oral drugs regularly and they have fear about taking insulin causing uncontrolled diabetes (high HbA1C level)." (PMID 38827868, 2024). "Owing to the high levels of SB/PI having impacts on basal insulin levels, both of them can increase the risk of diabetes significantly." (PMID 39469577, 2024). "Studies of rare, monogenic forms of diabetes have highlighted the key role of fetal insulin, since rare single gene mutations in the fetus that reduce insulin secretion are generally associated with a reduced birth weight." (PMID 38633783, 2024). "Diabetes mellitus is a serious health problem characterized by insufficient insulin secretion or a weakened body response to insulin, causing dysregulation of carbohydrate metabolism, which in turn leads to a sustained increase in blood glucose levels." (PMID 38628588, 2024). "In line with the previous literature, ML consistently identified 3 key factors—diabetes duration, age, and the use of insulin—as the top risk factors for both DKD and DR." (PMID 38546730, 2024). "Instead, we identified a unique cluster-combined insulin-resistant and deficient diabetes (CIRDD), previously reported in the Indian Population3." (PMID 39217248, 2024). "Subsequent research revealed that IGF2BP2 variants diminish glucose-stimulated insulin secretion in the initial phase of diabetes progression, indicating an impact on pancreatic β-cell function." (PMID 39659616, 2024). "Second, clinicians should optimize adherence among high-risk patients with longer diabetes duration, insulin use, adverse effects, lower education, and income levels." (PMID 39469399, 2024). "This precision is particularly relevant given the close association between visceral fat and adipocytokine production, insulin sensitivity, and the heightened risk of diseases such as diabetes and hypertension." (PMID 39625889, 2024). "High number of diabetes patients struggling to manage their uncontrolled glycemia can be partially linked to the expensive nature of insulin." (PMID 38910730, 2024). "These diseases are attenuated by the antioxidant and anti-inflammatory activity of these fatty acids, which also decrease the risk of diabetes by improving insulin sensitivity." (PMID 38541047, 2024). "Diabetes mellitus (DM), caused either by deficient insulin secretion or damaged of pancreatic β cell consists of type I and type II DM." (PMID 38545341, 2024).
diabetes (continued). "The increasing diabetes prevalence is associated with obesity and fatty acid release, reduced insulin levels in muscles, and fat accumulation in liver, which disrupts glucose homeostasis." (PMID 39295999, 2024). "Diabetes mellitus (DM) is a life-changing metabolic condition caused by abnormal insulin production, receptor activation, or both." (PMID 39092234, 2024). "Heterozygous missense mutations in the insulin gene are a common cause of permanent neonatal diabetes, another monogenic form of diabetes, but are occasionally identified in patients with MODY phenotypes." (PMID 39027635, 2024). "Tracking evolution of islet inflammation: Type 1 diabetes mellitus (T1D) is an autoimmune disorder, characterized by a progressive loss of pancreatic β-cells, a decrease in insulin secretion, and an increase in blood glucose levels." (PMID 38979061, 2024). "The results suggest that NIDDM is linked to an increased risk of dementia, particularly in elderly individuals with insulin-treated diabetes." (PMID 39571101, 2024). "Diabetes mellitus (DM) is a chronic metabolic illness marked by high blood sugar levels due to underlying dysfunction of insulin secretion, action, or both, and is a major public health concern, with rapidly increasing prevalence worldwide." (PMID 39583515, 2024). "Patients with higher levels of C-peptide (an indicator of endogenous insulin production) exhibited superior metabolic control and a diminished risk of chronic complications associated with diabetes." (PMID 39456927, 2024). "Duration of diabetes at baseline was positively associated with HbA1c, insulin dose and IDAA1c levels." (PMID 38517484, 2024). "Patients with blood glucose levels above 11 mmol/L due to poor diabetes control, steroid use, or targeted therapy causing hyperglycemia require insulin to optimize blood glucose before surgery." (PMID 39199594, 2024). "The association between maternal GBS colonization and diabetes severity as indicated by glycemic control and medical management (insulin treatment vs. lifestyle modification) requires further study." (PMID 39033123, 2024). "Type 2 diabetes mellitus (T2DM) is a heterogeneous disease characterized by chronic high blood glucose levels caused by impaired insulin release or its effects." (PMID 38358819, 2024). "The abnormal function of α-cells in diabetes is mainly caused by impairment of insulin release or action leading to failure of glycemic control." (PMID 39337311, 2024). "Type 1 diabetes mellitus is an autoimmune condition resulting in the destruction of pancreatic islet β-cells, caused by insulin resistance coupled with inadequate insulin secretion." (PMID 39770344, 2024). "Type 2 diabetes mellitus (T2DM) is characterized by a relative deficiency of insulin, primarily caused by beta cell dysfunction and external insulin resistance." (PMID 38658742, 2024). "Evidences have shown that developing diabetes has significant correlation with increasing age, increasing insulin resistance (IR),inadequate insulin production, and other risk elements." (PMID 39132231, 2024). "What is the association of a state-level $100 insulin copayment cap with out-of-pocket spending, treatment adherence, and health care services use for diabetes-related complications?" (PMID 39141389, 2024). "It should be noted that high levels of physical fitness are associated with greater insulin sensitivity favouring better management and control of diabetes." (PMID 38305822, 2024). "The leading causes of diabetes are the malfunctioning of islet cells and the body’s reduced sensitivity to insulin." (PMID 38800472, 2024). "Flavonoids such as quercetin have been shown to mitigate the risk of CVDs during pre-diabetes by improving endothelial function, reducing inflammation and enhancing insulin sensitivity." (PMID 39596174, 2024).